NFIA (nuclear factor I A)
Diseases named in the same sentence as NFIA in open-access papers (continued):
Sharing a sentence is not in itself a finding about the gene and the disease.
invasive breast carcinoma (1 paper, 2020). A carcinoma that infiltrates the breast parenchyma. "However, the NFIA mRNA level was upregulated in invasive breast carcinoma in Finak’s database." (PMID 32219034, 2020).
kidney chromophobe cell carcinoma (1 paper, 2020). "Contrary to kidney chromophobe cell carcinoma, expression of NFIA and NFIB was upregulated in kidney papillary cell carcinoma and expression of NFIC and NFIX was reduced." (PMID 32219034, 2020). "In addition, expression of NFIA and NFIB was downregulated in kidney chromophobe cell carcinoma, whereas expression of NFIC and NFIX was upregulated." (PMID 32219034, 2020).
kidney clear cell carcinoma (1 paper, 2020). "Consistent with the trend observed in the Oncomine database, NFIA, NFIB and NFIX were significantly overexpressed in kidney clear cell carcinoma compared with normal kidney tissue." (PMID 32219034, 2020).
large cell lung carcinoma (1 paper, 2020). "According to Garber’s database, NFIA expression was also downregulated in lung adenocarcinoma and large cell lung carcinoma." (PMID 32219034, 2020).
liver cancer (1 paper, 2020). An epithelial or non-epithelial malignant neoplasm that arises from the liver. "For liver cancer, analysis using the Oncomine database revealed only NFIA mRNA level was significantly downregulated in tumor tissues according to Wurmbach’s dataset." (PMID 32219034, 2020). "In the KM plotter database, high NFIA and NFIX expression predicted better OS and disease-specific survival (DSS) in liver cancer patients." (PMID 32219034, 2020).
lung adenocarcinoma (1 paper, 2020). A carcinoma that arises from the lung and is characterized by the presence of malignant glandular epithelial cells. "Using the same thresholds (p-value = 0.01; fold change = 2; gene rank: 10%, data type: mRNA), in Okayama and Hou’s analysis, the NFIA mRNA expression level was significantly lower in lung adenocarcinoma." (PMID 32219034, 2020). "Decreased NFIA and NFIB expression predicted worse OS and FP in lung adenocarcinoma patients." (PMID 32219034, 2020). "Low mRNA expression of NFIA and NFIB was significantly associated with OS and first progression in lung adenocarcinoma, but not in lung squamous cell carcinoma." (PMID 32219034, 2020).
lung carcinoma (1 paper, 2020). "In lung cancer, expression of NFIA and NFIB was correlated with better prognosis." (PMID 32219034, 2020).
Lung squamous cell carcinoma (1 paper, 2020). "Lung squamous cell carcinoma patients with NFIA gene alteration showed worse OS compared with lung squamous cell carcinoma patients without NFIA gene alterations." (PMID 32219034, 2020). "However, in SCLC and squamous cell lung carcinoma, opposite results were observed for NFIA in reporter IMAGE:364302 (high expression) and IMAGE:813154 (low expression)." (PMID 32219034, 2020).
lymph node metastasis (1 paper, 2018). "The results showed that high NFIA expression correlated with poor differentiation, lymph node metastasis, and short overall survival (OS) and disease‐free survival (DFS) in patients with ESCC." (PMID 29577671, 2018). "The results showed that high NFIA expression correlated significantly with poor differentiation, lymph node metastasis, and advanced TNM stage in patients with ESCC." (PMID 29577671, 2018). "High NFIA expression (HR = 3.388, 95% CI = 1.801–6.371, P < 0.001), lymph node metastasis (HR = 3.628, 95% CI = 2.020–6.517, P < 0.001), and T‐stage (HR = 2.228, 95% CI = 1.166–4.256, P = 0.015) were also independent risk factors for DFS in ESCC." (PMID 29577671, 2018). "Besides, high NFIA expression (HR = 3.044, 95% CI = 1.697–5.457, P < 0.001), T‐stage (HR = 2.156, 95% CI = 1.173–3.963, P = 0.013), and lymph node metastasis (HR = 4.116, 95% CI = 2.442–6.936, P < 0.001) were prognostic risk factors for DFS." (PMID 29577671, 2018). "NFIA expression was higher in cancer tissues with lymph node metastasis than in those without lymph node metastasis." (PMID 29577671, 2018). "High NFIB but not NFIA expression correlated with poor differentiation, lymph node metastasis, and short OS and DFS time in patients with EJA." (PMID 29577671, 2018).
nasopharyngeal carcinoma (1 paper, 2020). A carcinoma arising from the nasopharyngeal epithelium. "NFIA and NFIX were reduced in tonsillar carcinoma, nasopharyngeal carcinoma, and oral cavity squamous cell carcinoma, respectively." (PMID 32219034, 2020).
neuroendocrine tumors (1 paper, 2022). "The opposite impact of TF score on the survival of NEL and NBL may attributed to BATF3, GMEB1 and REST, since NFIA and ZNF281 showed uniform influence on the survival of the two neuroendocrine tumors." (PMID 36713370, 2022).
oligodendroglioma (1 paper, 2021). A well-differentiated (WHO grade II), diffusely infiltrating neuroglial tumor, typically located in the cerebral hemispheres. "Nuclear factor IA is lost as part of chromosome 1p31 and low expression of NFIA is associated with oligodendrogliomas." (PMID 34012965, 2021). "Strikingly, overexpression of NFIA in a mouse model of oligodendroglioma can convert the tumor to an astrocytoma subtype." (PMID 34012965, 2021).
prostate (1 paper, 2024). "Also they showed that miR-671–5p modulates nuclear factor I A (NFIA), thereby contributing to prostate tumorigenesis." (PMID 39007129, 2024).
rhabdomyosarcoma (1 paper, 2023). A rare aggressive malignant mesenchymal neoplasm arising from skeletal muscle. "NFIA is required for the proliferation of cervical cells, ZBTB18 for rhabdomyosarcoma, and TEAD3 for the urinary tract cells." (PMID 37297004, 2023).
Seizure (1 paper, 2023). A seizure is an intermittent abnormality of nervous system physiology characterized by a transient occurrence of signs and/or symptoms due to abnormal excessive or synchronous neuronal activity in the brain. "Next, to better understand the mechanisms that cell-specific NFIA upregulation controls astrocyte reactivity in 4-AP-induced seizure model, we test the effect of NFIA knockdown on the expression of TRPV4 and its functional activity in primary cultured astrocytes." (PMID 37880726, 2023).
tumor (31 papers, 2011 to 2026). "Chi-square analysis revealed that NFIA level was significantly associated with tumor metastasis (P = 0.004)." (PMID 33144585, 2020). "Lastly, by sequencing HCC1937 and HCC2337, a tumor cell line and matched lymphocyte cell line derived from the same patient, respectively, we sought to determine whether NFIA-EHF was a germline mutation or an acquired somatic mutation." (PMID 22032724, 2011). "Furthermore, despite utilizing different approaches and driver mutations to induce tumor formation, the loss of NFIA or OLIG2 was also accompanied by significant decreases in tumor cell proliferation resulting in an increase in survival for their respective mouse models." (PMID 32573857, 2020). "It has been observed that miR-212-3p exerts anti-tumor effects by targeting NFIA, thereby inhibiting cell proliferation directly through NFIA regulation." (PMID 39777350, 2024). "Functions of the NFIA gene are better understood in brain development, although recent findings link its role to tumor progression." (PMID 37297004, 2023). "We confirmed for the first time that NFIA, regulated by miR-671, could inhibit PCa cells proliferation, migration and invasion, and function as a tumor suppressor in PCa." (PMID 33144585, 2020). "In addition, SOX10 has been shown to affect cell fate decisions in neural lineage development in mice, and was described to antagonise the function of the transcription factor NFIA in driving astrocytic differentiation in normal development and later, overexpression in mouse tumour models." (PMID 33339831, 2020). "Note that NFIA is an integral transcriptional component of myeloid cells and plays critical role for myeloid differentiation and lineage commitment, and the NFIA knockdown can alter the suppressive function of G-MDSCs, promote the antitumor immune responses, and delay tumor progression in mice." (PMID 29535722, 2018). "Stemness-related genes SOX4 and NFIA exhibited expression in both, mouse xenograft and hGliCS, with SOX11 showing high expression exclusively in hGliCS, compared to monocultured S24 tumor cells." (PMID 40188875, 2026). "When focusing on regulatory patterns, we found that CAFs displayed distinct cell type-specific TFs alongside shared TFs widely involved in carcinogenesis, including various tumor promoters or tumor suppressors, such as KLF4, NFIA, TCF21, NFKB1, and EGR1." (PMID 39872221, 2025). "Furthermore, NFIA was found to be upregulated in CIC‐mutant cells compared with CIC‐wild type cells in a single‐cell gene expression analysis of a primary ODG, indicating that the increased NFIA expression that we observed in CIC‐KO (IDH1‐R132H) cells may be relevant in a primary tumour context." (PMID 34767259, 2022). "miR-223 regulates several targets, such as NLRP3, NFIA, and PARP1, that are involved in the induction of apoptotic mechanisms observed in AYA-RMS tumor tissues." (PMID 31533233, 2019). "Higher NFIA levels were observed in GBM cell lines and human tumor sections compared with astrocytes and non-tumor tissues, respectively." (PMID 28323865, 2017). "In extensive studies of murine neural developmental pathways and their potential role in human gliomagenesis, SOX9-dependent activation of the transcription factor nuclear factor I-A (NFIA) was shown to antagonise SOX10 function and result in astrocytic differentiation of the tumour cells." (PMID 33339831, 2020). "In our study, we found NFIA could directly bind to the promoter region of CRYAB, and CRYAB mediated the tumor-suppressive activity of NFIA in PCa." (PMID 33144585, 2020). "Thus both NFIA and NFIB appear to function in a genetic context-dependent manner as either tumour suppressors or oncogenes." (PMID 27083054, 2016). "Some show marked differential expression in a single non-SHH subgroup,such as NFIA (Group 3 tumours) and FGF13 (Group 4 tumours), orin more than one subgroup (e.g. TGIF2 and MYT1L), suggestingthat these genes may be relevant to MB in general." (PMID 24252690, 2013).
cancer (18 papers, 2015 to 2025). A tumor composed of atypical neoplastic, often pleomorphic cells that invade other tissues. "NFIA (nuclear factor I A) encodes a member of the NF1 (nuclear factor 1) family of TFs known to act as oncogenes in several cancer models." (PMID 33371395, 2020). "The associated cancer functional states of hsa-mir-21 predicted target genes (RP2, NFIA, SPRY1 and TGFBI) was first revealed." (PMID 36035369, 2022). "In 53 of the 69 studies, 14 types of cancers showed decreased NFIA mRNA expression level compared with normal tissues; however, in 16 studies, the opposite results were observed." (PMID 32219034, 2020). "However, the key target of NFIA in the role switch between cancer suppression and cancer genesis are unclear at present." (PMID 36035369, 2022). "Therefore, we speculated that the specificity of cancer immune microenvironment may account for the role switch of NFIA in cancers." (PMID 36035369, 2022). "MiR-212 is regulated by nuclear factor IA (NFIA) and hypoxia-inducible factor-1α (HIF-1α) and has been identified as a potential biomarker for cancer diagnosis and treatment." (PMID 39062744, 2024). "The transcriptional expression of RP2, NFIA and SPRY1 in four cancer grades was significantly higher than that of the normal." (PMID 36035369, 2022). "The transcriptional expression of RP2, NFIA, SPRY1 and TGFBI in four cancer stages was significantly higher than that of the normal." (PMID 36035369, 2022). "NFIA, NFIB and NFIC expression levels were reduced in cancer tissues evaluated using mRNA HiSeq expression data from the TCGA database." (PMID 32219034, 2020). "Recent studies revealed that NFIs, especially NFIA and NFIB, also function in the development or progression of cancers." (PMID 29577671, 2018). "The nuclear factor I (NFI) family members, especially NFIA and NFIB, play essential roles in cancers." (PMID 29577671, 2018). "We found that MSC, NFIA, NFIC and TCF21 were significantly effective regulons for fibroblasts in more than three cancers, indicating that they might be crucial in driving changes in cell state." (PMID 36772945, 2023). "Additionally, there are very significant differences between the two groups in methylation of specific genes known to be important in UM and in cancer progression in general, including PTEN, NFIA, IL12RB2, RASSF1, and HDAC4." (PMID 33092094, 2020). "NFIA and NFIB were expressed if any only in basal cells of normal esophageal epithelia, mainly located in the nucleus, while in ESCC tissues, NFIA was highly expressed in cancer cells, located in both the nucleus and cytoplasm." (PMID 29577671, 2018).
infection (4 papers, 2017 to 2024). The state of being infected such as from the introduction of a foreign agent such as serum, vaccine, antigenic substance or organism. "In the 72 h infection group, the mRNA expression was up-regulated and the protein expression was down-regulated in seven groups, namely the TNXB, NFIA, PROC, SPIN1, NR2C2 nuclear receptor subfamily 2 group C member 2, Carboxypeptidase D and ARHGAP11B." (PMID 36496794, 2022). "In the 72 h infection group, the mRNA expression was up-regulated and the protein expression was down-regulated in 7 groups, namely the TNXB, NFIA, PROC, SPIN1, NR2C2 nuclear receptor subfamily 2 group C member 2, Carboxypeptidase D and ARHGAP11B." (PMID 36496794, 2022). "Although the transcription factor NFIA was inhibited, ATF2 was activated by vvIBDV infection." (PMID 28086922, 2017).
neurological disorders (3 papers, 2013 to 2017). "Mutations in the human orthologs of some genes carrying NSph-T-DMR, such as LIG4 and NFIA, are associated with neurological disorders." (PMID 23387509, 2013).
neurodevelopmental disorder (2 papers, 2021 to 2022). A behavioral and cognitive disorder with onset during the developmental period that involves impaired or aberrant development of intellectual, motor, or social functions. "Therefore, this is the first case report of NFIA missense variant associated with the neurodevelopmental disorder." (PMID 33973697, 2021). "Truncating variants or intragenic deletion of the NFIA gene are known to cause the human neurodevelopmental disorder known as NFIA‐related disorder, but no patient heterozygous for a missense mutation has been reported." (PMID 33973697, 2021).
CNS tumours (1 paper, 2022). "In summary, these examples highlight the impacts of CIC‐KO and IDH1‐R132H on enhancers at genes associated with CNS tumours and, regarding NFIA, illustrate an interesting case of an enhancer whose activity is differentially regulated by CIC loss in an IDH1‐dependent fashion." (PMID 34767259, 2022).
genetic disorder (1 paper, 2022). "First, all those patients with NFIA alterations and pathogenic genetic variants disrupting additional protein-coding sequences were excluded, since a thoughtful selection of cases is the most important step to accurately delineate genotype–phenotype correlations of a genetic disorder." (PMID 36553517, 2022).
NFIA also shares sentences with these, for which no sentence is quoted: autism (2 papers); Chiari malformation type I (2); hydronephrosis (2); Infertility (2); kidney (2); polymicrogyria (2); acute myelocytic leukemia (1); adenocarcinoma (1); autism spectrum disorder (1); Barrett esophagus (1); central nervous system malformation (1); Cerebellar atrophy (1); cervical cancer (1); chronic kidney disease (1); clear cell sarcoma (1); cognitive deficits (1); colon cancer (1); cortical atrophy (1); cryptorchidism (1); cutaneous squamous cell carcinoma (1); gastric cancer (1); hepatoma (1); hyperlipidaemia (1); hypothyroidism (1); hypoxic-ischemic encephalopathy (1); Inguinal hernia (1); intrauterine growth restriction (1); Leukaemia (1); lymphoma (1); medulloblastoma (1).
A further 14 diseases each share a sentence with NFIA in 1 paper.